MIR503 (microRNA 503)
Synonyms: hsa-mir-503; MIRN503; mir-503
Gene: MicroRNA gene on chromosome X (134,546,328 to 134,546,398, reverse strand). Ensembl gene ENSG00000208005.
Gene Ontology:
Biological process: miRNA-mediated post-transcriptional gene silencing
Cellular component: RISC complex
Diseases named in the same sentence as MIR503 in open-access papers:
MIR503 is named in the same sentence as 3 diseases in open-access papers, as found by Europe PMC text mining. Sharing a sentence is not in itself a finding about the gene and the disease. The quoted sentences say what the papers report.
ovarian carcinoma (1 paper, 2022). A malignant neoplasm originating from the surface ovarian epithelium. "MIR503 host gene (MIR503HG) acts as an important tumor suppressor in many human cancers, but its role and regulatory mechanism in ovarian cancer need to be further studied." (PMID 35771155, 2022).
cancer (2 papers, 2019 to 2022). A tumor composed of atypical neoplastic, often pleomorphic cells that invade other tissues. "Long non‐coding RNA MIR503 host gene (MIR503HG) is located on chromosome Xq26.3, and has been found to be deregulated in many types of human malignancy and function as tumour suppressor or promoter based on cancer types." (PMID 31062436, 2019).
MIR503 also shares sentences with these, for which no sentence is quoted: tumor (2 papers).